MIR581 (microRNA 581)
Synonyms: hsa-mir-581; MIRN581
Gene: MicroRNA gene on chromosome 5 (53,951,504 to 53,951,599, reverse strand). Ensembl gene ENSG00000207627.
Gene Ontology:
Biological process: miRNA-mediated post-transcriptional gene silencing
Cellular component: RISC complex
Homologues: Orthologues: chimpanzee ptr-mir-581 (99% identical), macaque mml-mir-581 (95% identical).